KRAS (KRas proto-oncogene, GTPase)
Diseases named in the same sentence as KRAS in open-access papers (continued):
Sharing a sentence is not in itself a finding about the gene and the disease.
cancer (continued). "The recent discovery of the potential dual targeting of autophagy and MEK in KRAS mutant cancer raised the intriguing possibility to use CBD in combination with autophagy inhibitors such as CQ or HCQ." (PMID 33802014, 2021). "In this review, we discuss the development of drugs targeting KRAS and KRAS signaling-related proteins, including small-molecule TPD-based chemicals, and their potential applications in treating KRAS mutant cancers." (PMID 34830024, 2021). "In contrast to Galectin-9, the central role of KRAS in carcinogenesis and progression of cancer has been known for decades, even though KRAS had long been dubbed an ‘undruggable’ target." (PMID 34496946, 2021). "It has been demonstrated that the wild-type KRAS is a proto-oncogene that is frequently activated during many types of cancer progression." (PMID 35004317, 2021). "Tipifarnib, a highly selective and potent farnesyltransferase inhibitor, originally developed by Janssen as a KRAS inhibitor in the early 2000s, has displayed sporadic clinical activity in several unstratified cancer patient populations." (PMID 35008248, 2021). "Recently, in genome-wide CRISPR screens, FLIP was identified as the top dependency in KRAS mutant versus KRAS wild-type cancers." (PMID 34073507, 2021). "Using FR054 to inhibit glycosylation reactions further enhances the anticancer activity of BI-2852 against PDAC cells, supporting that the hexosamine biosynthesis pathway is a potential target for the treatment of KRAS-mutant cancers." (PMID 34607583, 2021). "Overall, KRAS-mediated metabolic reprogramming in cancer offers new therapeutic approaches for the treatment of KRAS-driven cancers." (PMID 34947990, 2021). "Some specific inhibitors of the mutant KRAS have been developed in recent years, and they are considered promising for cancer treatment." (PMID 33670598, 2021). "Expressed recombinant immunotoxins were analyzed for their effects on cell proliferation by the MTT assay and targeted specificity by cell-based ELISA on KRAS-positive and KRAS-negative cancer cells." (PMID 33959410, 2021). "In particular, our group and others have recently reported the clonal expansion of cancer-associated mutations such as PIK3CA, KRAS, and PTEN in histologically normal endometrial glands using single gland sequencing or laser capture microdissection." (PMID 34442357, 2021). "The high rate of glutamine uptake plays a required role in the uptake of essential amino acids and in maintaining the activation of target of rapamycin kinase in cancer cells, especially those driven by KRAS." (PMID 33790982, 2021). "Another mechanism allowing the bypassing of KRAS inhibition in preclinical cancer cell lines is the amplification of a transcriptional coactivator, YAP1." (PMID 34064232, 2021). "Experiments in cell culture and animal models have confirmed that the development of several cancers relies on the sustained expression and signal transduction of KRAS." (PMID 34134622, 2021). "KRAS is a highly desirable target for cancer therapy; however, the development of pharmacological small molecules for mutant KRAS remains challenging, and most of the identified inhibitors are still in early-stage clinical trials." (PMID 33740988, 2021). "Other studies have identified amplification of the transcriptional coactivator YAP1 as a means of bypassing KRAS inhibition in cancer cell lines." (PMID 33466360, 2021). "Understanding biological characteristics and precise signaling of KRAS proteins is essential for targeted cancer therapy." (PMID 34830757, 2021). "Unfortunately, none of these mechanisms have resulted in approvals for these strategies in KRAS G12C mutant cancers." (PMID 34845311, 2021). "Nevertheless, experiments are currently underway to evaluate the effects of new panRAF inhibitors, such as LXH254 and belvarafenib, administrated alone or in combination with other drugs, on KRAS-driven cancers." (PMID 34947990, 2021).
cancer (continued). "In support of this notion, combinations of SFK and MEK inhibitors exhibited synergistic effects on PDAC patient-derived cell lines and xenografts and other KRAS-mutant cancer models both in vitro and in vivo." (PMID 34680275, 2021). "KDR, SH2D2A, SRC, and KRAS were included in the VEGF signaling pathway, of which variants were associated with cancer recurrence when they were assessed simultaneously." (PMID 34599262, 2021). "In this study, we discuss small-molecule inhibitors, TPD-based small-molecule chemicals for targeting RAS pathway proteins, and their potential applications for treating KRAS-mutant cancers." (PMID 34830024, 2021). "KRAS and PTEN mutations were more frequent from patients with advanced cancers by cancer antigen markers." (PMID 35003350, 2021). "Mutant KRAS DNA of the two cancer cells and wild-type KRAS DNA of BEAS2B cells were diluted in the genomic DNA isolated from the PBMCs of a healthy donor, respectively." (PMID 33467412, 2021). "There has been a significant progress made in this area resulting in successful targeting of KRAS or downstream effectors in several cancer types, with multiple agents in clinical trials." (PMID 33801965, 2021). "It is worth noting that the KRAS mutation is also associated with the upregulation of HIF-1α and the Warburg effect in cancer cells." (PMID 34540683, 2021). "Using NMR-based metabonomics, we compared wildtype (WT)-KRAS and mutant KRAS effects on cancer cell metabolism using metabolic profiling of the parental KRASG13D/+ HCT116 cell line and its isogenic, derivative cell lines KRAS+/– and KRASG13D/–." (PMID 34822010, 2021). "We observed synergistic effects for such drug combinations against cancer cell lines as well as CDX, and PDX models harboring the KRAS G12C mutation." (PMID 34151545, 2021). "Control (GFP-expressing) flat cells grew to 30% of maximal growth in glutamine-free medium whereas KRASG12V-expressing cells did not grow at all in the absence of glutamine, consistent with the requirement of glutamine in KRAS-driven cancer cells." (PMID 33742081, 2021). "Despite this prevalence and its prominent status as a cancer drug target, molecules aimed at disrupting KRAS signaling have proven challenging, and mutant KRAS protein has remained an intractable therapeutic target for over two decades." (PMID 34065438, 2021). "RAS genes (HRAS, KRAS, and NRAS) are the most frequently mutated genes in cancer cells, showing a mutation frequency of 30% in all cancer cells." (PMID 34830024, 2021). "There was significantly less KRAS wild‐type in pancreatic body/tail cancers than pancreatic head cancers (2.9% vs 17.6%, P = 0.004)." (PMID 33452856, 2021). "A simple mathematical model was built, containing the main regulatory elements of the regulatory network to provide a detailed qualitative description about the control network in KRAS mutant cancer cells." (PMID 33925206, 2021). "In recent years, there has been much excitement surrounding SHP2 inhibition as a potential therapeutic for KRAS-driven cancers." (PMID 34725361, 2021). "Overall, systematic studies reported here made key advances on this peptide series and used rigorous controls to validate the potential of blocking mutant-KRAS function in cancer cells via binding to this unique epitope." (PMID 35024121, 2021). "Cancer cells and tumors also have variable degrees of KRAS dependency, and the effects of mutant KRAS on cellular reprogramming are tissue-context-dependent." (PMID 33809660, 2021).
cancer (continued). "Depletion of Phafin2 inhibits macropinosome internalization and maturation and prevents KRAS-transformed cancer cells from utilizing extracellular protein as an amino acid source." (PMID 34772942, 2021). "Independently of the cancer type, mutant KRAS has been considered an undruggable target for more than three decades; nevertheless, new approaches for blocking KRAS continue to be developed." (PMID 34684076, 2021). "Despite the indispensability of PLK1 in mutant KRAS‐driven cancer, efficacy of PLK1 inhibitors as monotherapy has been thwarted by poor response rates of patients." (PMID 34369083, 2021). "In KRAS-driven cancers, there is crosstalk between many signalling networks, including KRAS, PDGFR and MET, and many of these pathways are upstream of STAT3." (PMID 33658640, 2021). "The sustained expression and signaling of KRAS results in the progress of many cancers thus make it the high-priority target in clinical therapeutic implications." (PMID 34032581, 2021). "Mutations in KRAS enhance GTP binding, resulting in a constitutively active form of KRAS, sufficient for oncogenic transformation and induction of cancer development." (PMID 34003553, 2021). "Frequently observed oncogenic mutations, such as KRAS, PI3K, and PTEN, have been demonstrated to greatly enhance macropinocytosis in cancer cells." (PMID 34683931, 2021). "While these studies support the initiating role of KRAS in cancer development, they underscore the need for a comprehensive view of stage-specific and cell type-specific cancer dependencies and novel rationale-based therapies." (PMID 33674596, 2021). "Tumors with KRAS mutations generally have poor prognosis as they appear to be resistant to most available systemic therapies, making KRAS a key target for cancer treatment." (PMID 32530390, 2021). "Trametinib has been shown to be effective in inhibiting the proliferation of BRAFV600E and KRAS mutant cancer cell lines." (PMID 33858332, 2021). "ATDC is overexpressed in the vast majority of human PDAC, whereas its conditional knockout in a KRAS induced pancreatic tumorigenesis murine model completely abrogated invasive cancer development." (PMID 34771695, 2021). "The cell viability assay was used to test a combination of AMG510 and IN10018 with diverse KRAS G12C mutant cancer cell lines." (PMID 34151545, 2021). "Nevertheless, the effects of KRAS inhibition can be increased through the co-inhibition of other nodes important for cancer development." (PMID 33670598, 2021). "Constitutive activation of the KRAS oncoprotein triggers an intracellular cascade in cancer cells, leading to uncontrolled cell proliferation of cancer cells and aberrant cell survival states." (PMID 35070984, 2021). "HotPho successfully identifies likely functional mutational clusters and phosphosites in known cancer proteins, including EGFR, KIT, and KRAS/HRAS/NRAS, many of which are in kinase domains." (PMID 33875650, 2021). "The enrichment of the pathways in the epithelial-mesenchymal transition process and KRAS signaling up shows that PI3K-Akt signaling supports the critical role of these genes in cancer development." (PMID 34966741, 2021). "Analyzing recently published KRAS screens, we also find a subclonal expansion of KRAS mutant cancer cells following Cas9 expression." (PMID 34764240, 2021). "Our results furthermore confirm our recently proposed K-Ras-directed HIF1α and Gal3-dependent mechanism of action of Hsp90 inhibitors, suggesting that KRAS mutant cancers should be considered for the evaluation of Hsp90 inhibitors in the future." (PMID 34199986, 2021). "12VC1 selectively captured endogenous KRAS from cancer cell lines PATU8902 and H358 that contain KRAS(G12V) and KRAS(G12C), respectively, but not from growth factor stimulated HEK293T cells containing only wild-type RAS." (PMID 33976200, 2021).
cancer (continued). "The combination of KRAS G12C and FAK inhibitors produces synergistic antitumor effects, providing a regimen to obtain strengthened and prolonged treatment outcomes for KRAS G12C mutant cancers." (PMID 34151545, 2021). "Sotorasib is a first of its kind KRas G12C mutant targeting anti-cancer therapy and is currently approved for the treatment of non-small cell lung cancer (NSCLC) (Clinical Trial NCT03600883)." (PMID 34680208, 2021). "Other mutated cancer genes included those involved in Wnt signaling (APC, AMER1), mitogen signaling (KRAS, BRAF), epigenetic modification (ARID1A, ARID2, DNMT3A, NCOA3) and DNA repair (RAD50, BRIP1, ERCC5, RECQL4)." (PMID 33776923, 2021). "We predicted that the addition of both pharmacologic ascorbate and chloroquine is able to block both KRAS and mTOR pathways: in this case, no GLUT1 expression is observed, meanwhile autophagy, essential for KRAS mutant cancer cells, is blocked." (PMID 33925206, 2021). "McCormick F stated that KRAS targeting for cancer treatment was effective both when directly targeting the protein or using indirect approaches to target it, such as siRNA or harnessing the immune system." (PMID 34134622, 2021). "Mutant KRAS in cancer cells stimulates cytokine receptor expression such as such as IL4R, IL2Rγ, and IL13Rα1 that, in turn, facilitate the Jak1-Stat6-cMyc pathway activation by IL-4 and IL-13." (PMID 33777798, 2021). "In cancer cells the mutant KRas accumulates in an elevated GTP-bound proportion and thus leads to a constantly activated form." (PMID 35069209, 2021). "This is concordant with the fendiline-led inhibition of the KRASG12V-dependent MAPK signaling, compromised the proliferation the mutant KRAS-transformed cancer cells, as well as decreased the sizes of mutant KRAS-dependent tumors in xenograft models." (PMID 34680072, 2021). "The key question from the perspective of cancer treatment is the extent to which KRAS mutant cancers retain dependence on KRAS." (PMID 33674596, 2021). "ERBB2, EGFR and KRAS have FDA-approved drugs for use in cancer therapy, whereas CDKN2A has biological evidence for targetability, but associated drugs are not yet standard-of-care." (PMID 34298611, 2021). "This study thus illustrates the mechanism of resistance of cancer to the treatment of KRAS G12C inhibitor, as well as an innovative combination therapy to improve treatment outcomes for KRAS G12C mutant cancers." (PMID 34151545, 2021). "Nanoliposome packaged miR-193a-3p has shown broad applicability as a therapeutic agent to target KRAS-mutant cancer." (PMID 34503246, 2021). "In mouse models of KRAS-mutant cancer, the ATRi ceralasertib attenuated radiation-induced CD8 T cell exhaustion and potentiated CD8 T cell activity." (PMID 34885119, 2021). "Aberrant expression of TEAD has been documented to influence well‐known cancer genes such as KRAS and BRAF, with its transcriptional output implicated in various processes including cancer metabolism, tumour progression and cancer metastasis." (PMID 33570213, 2021). "Since the direct targeting of KRAS has been difficult in all cancers, inhibitors focusing on targeting RAF/MEK/ERK have been generated." (PMID 33801965, 2021). "In particular, considerable efforts have been made to treat KRAS-induced cancers by directly and indirectly controlling the activity of KRAS." (PMID 34830024, 2021). "Recently, researchers have argued that the PI3K-AKT pathway requires RTK-induced activation, usually involving SHP2 as a critical mediator in KRAS-mutant cancers." (PMID 34790119, 2021). "In the recent years, CRISPR applications have been widely used to generate mutation-based in vivo and in vitro models, in order to study therapeutic approaches in KRAS-driven cancers, specifically in computational settings." (PMID 34781949, 2021).
cancer (continued). "Unfortunately, KRAS and NRAS, the major RAS isoforms that are mutated in adult cancers, can be alternatively prenylated by gerangeranyltransferases, and FTIs failed in Phase III clinical trials for KRAS-mutated colorectal and pancreatic cancers." (PMID 33924994, 2021). "Oncogenic mutations in KRAS are very frequent in PDAC, with the prevalence being around 90%, and this gene is usually already mutated in the early stages of cancer development." (PMID 33670598, 2021). "12VC1 showed potent efficacy in inhibiting the signaling and proliferation of RAS-driven cancer cell lines containing KRAS(G12V) and (G12C) and in a mouse xenograft model." (PMID 33976200, 2021). "Diverse CDX and PDX models of KRAS G12C mutant cancer are examined and synergistic benefits from the combination therapy are consistently observed." (PMID 34151545, 2021). "In conclusion, this work is the first to describe the development of recombinant immunotoxins to target KRAS-positive cancer cells coupled with a potent Hydra toxin." (PMID 33959410, 2021). "In particular, KRAS mutant cancer cells exploit amino acids (AAs) such as glutamine and leucine, to accelerate energy metabolism, redox balance through glutathione synthesis and macromolecule biosynthesis." (PMID 34003553, 2021). "Hyperactive Ras/Raf/MEK/ERK1/2 signaling exists in over 85% of cancer cases, which are caused by genetic alterations of its upstream activators, especially RAS family protein isoforms (KRAS, NRAS, HRAS)." (PMID 34828284, 2021). "In this result, these commonly related genes including TERT, KRAS, and CDKN2A were also highly associated with cancer progression." (PMID 34442467, 2021). "In previous retrospective studies, KRAS p.G12D was found a poor prognostic factor for OS across different cancer types." (PMID 33350171, 2021). "Of the three RAS family members, inhibition of mutant KRAS by WT KRAS is the most consistently observed across cancer types." (PMID 33924994, 2021). "It is widely accepted that oncogenic KRAS is conductive to promote cell survival, proliferation, and cytokine secretion to acting on stromal cells to promote cancer malignancy by activating intracellular PI3K, MAPK, or RAL‐GEF pathways." (PMID 33694292, 2021). "It has been reported that KRAS G12D cancer cells can increase the uptake of glucose and production of lactose, which ultimately results in glycolytic flux." (PMID 34638560, 2021). "Computational analysis and in vitro assays identified CDK1, one of the most promising lethal targets for KRAS-mutant cancer, as a target of miR-34c-3p." (PMID 32948832, 2021). "Many groups have described the potential antitumor effect of verteporfin, including that in KRAS-mutant cancer cells." (PMID 33830081, 2021). "The KRAS protein can accelerate growth in healthy cells as well as in cancer and it does this by activating various other proteins." (PMID 34590580, 2021). "Despite this, several KRAS-binding small molecules (e.g., Sotorasib, Adagrasib) have been recently developed to irreversibly inhibit the G12C missense mutant of KRAS, showing encouraging results in various cancer types, including non-small cell lung cancer." (PMID 34358103, 2021). "The mutant KRAS has been closely involved in the initiation of Warburg metabolism, the key role of KRAS signalling in the homeostasis of aerobic glycolysis which has been described in different types of cancer." (PMID 33925206, 2021). "Beyond the scope of cancer cells, it is entirely possible that the unique tissue-specific niche in which the KRAS-mutant cancer cells arise critically determines the behavior of these cancer cells, ultimately shaping the unique behavior of each cancer type." (PMID 34771644, 2021).